ZKSCAN3 (zinc finger with KRAB and SCAN domains 3)
Description:
Transcriptional factor that binds to the consensus sequence 5'-[GT][AG][AGT]GGGG-3' and acts as a repressor of autophagy. Specifically represses expression of genes involved in autophagy and lysosome biogenesis/function such as MAP1LC3B, ULK1 or WIPI2. Associates with chromatin at the ITGB4 and VEGF promoters. Also acts as a transcription activator and promotes cancer cell progression and/or migration in various tumors and myelomas.
Synonyms: Zf47; Zfp-47; ZFP47; ZNF306; ZNF309; ZSCAN13; ZSCAN35; ZFP306; dJ874C20.1; dJ874C20.1.
Tractability: PROTAC: UniProt records ubiquitination sites on it; ubiquitination databases record sites on it; its protein half-life has been measured.
Gene: Protein-coding gene on chromosome 6 (28,349,911 to 28,369,172, forward strand). Ensembl gene ENSG00000189298.
Subcellular location: Nucleus; Cytoplasm
Subcellular location (Human Protein Atlas): Nucleoplasm
Pathways (Reactome):
Gene expression (Transcription): Generic Transcription Pathway
Gene Ontology:
Molecular function: chromatin binding; DNA binding; DNA-binding transcription factor activity; DNA-binding transcription repressor activity, RNA polymerase II-specific; protein binding; RNA polymerase II cis-regulatory region sequence-specific DNA binding; sequence-specific DNA binding; DNA-binding transcription factor activity, RNA polymerase II-specific
Biological process: lysosome organization; negative regulation of autophagy; negative regulation of cellular senescence; negative regulation of DNA-templated transcription; negative regulation of transcription by RNA polymerase II; positive regulation of DNA-templated transcription; regulation of transcription by RNA polymerase II; regulation of DNA-templated transcription
Cellular component: cytoplasm; nucleoplasm; nucleus
Genetic constraint (gnomAD): Loss-of-function variants: 25 observed, 37.67 expected, observed/expected ratio (o/e) 0.66, 90% interval 0.48 to 0.93. The synonymous counts are far from expectation, so gnomAD's model fits this gene poorly and the ratio says little. Missense variants: 507 observed, 677.63 expected, observed/expected ratio (o/e) 0.75, 90% interval 0.69 to 0.81. Synonymous variants: 201 observed, 255.44 expected, observed/expected ratio (o/e) 0.79, 90% interval 0.7 to 0.88.
Homologues: Orthologues: chimpanzee ZKSCAN3 (99% identical), macaque ZKSCAN3 (97% identical), rabbit ZKSCAN3 (80% identical). Paralogues in human: ZKSCAN4 (85% identical), ZKSCAN8 (45% identical), ZKSCAN1 (43% identical), ZSCAN12 (41% identical), ZSCAN21 (41% identical), ZSCAN30 (40% identical), ZNF397 (40% identical), ZSCAN22 (38% identical), ZSCAN26 (38% identical), ZNF165 (37% identical), ZNF263 (36% identical), ZNF394 (35% identical), and 18 more.
Diseases named in the same sentence as ZKSCAN3 in open-access papers:
ZKSCAN3 is named in the same sentence as 39 diseases in open-access papers, as found by Europe PMC text mining. Sharing a sentence is not in itself a finding about the gene and the disease. The quoted sentences say what the papers report.
colorectal cancer (13 papers, 2013 to 2025). A primary or metastatic malignant neoplasm that affects the colon or rectum. "Analysis of clinical data from 450 colorectal cancer patients revealed that elevated ZKSCAN3 expression demonstrated a strong positive association with hepatic metastasis risk and higher serum carcinoembryonic antigen (CEA) concentrations." (PMID 40723888, 2025). "Potential involvement of ZKSCAN3 was reported in colorectal cancer, liver cancer, multiple myeloma, prostate cancer, bladder cancer, breast cancer, cervical cancer, and gastric cancer." (PMID 41393507, 2025). "When compared to adjacent normal tissues, ZKSCAN3 was found to be markedly overexpressed in several solid tumors, including colorectal cancer, gastric cancer, pancreatic ductal adenocarcinoma (PDAC), and non-small cell lung cancer (NSCLC)." (PMID 39519085, 2024). "As high Zkscan3 expression has been reported previously in colorectal cancer cells, we therefore evaluated CT26 cells and found that are Zkscan3-positive too." (PMID 34940950, 2022). "Overexpression of Zkscan3 has been observed in colorectal cancer, breast cancer, bladder cancer, and cervical cancer, suggesting a potential role for ZKSCAN3 in tumorigenesis." (PMID 34940950, 2022). "In colorectal cancer, ZKSCAN3 overexpression increased anchorage-independent growth in vitro, orthotopic tumor growth, and liver metastasis in vivo, as well as resistance to the treatment with 5-fluorouracil." (PMID 33672287, 2021). "In another study on colorectal cancer, ZKSCAN3 expression was interconnected with cancer-related proteins, i.e., carcinoembryonic antigen (CEA), VEGF, and AKT levels in the liver metastasis." (PMID 33672287, 2021). "ZKSCAN3 has been reported to be overexpressed in several human cancers such as colorectal cancer and prostate cancer and is proposed as a candidate oncoprotein." (PMID 30241382, 2018). "The authors showed that ZKSCAN3 knockdown in colorectal cancer cells inhibited anchorage-independent growth and orthotopic tumor growth, while ZKSCAN3 overexpression exerted opposite effects." (PMID 27411336, 2016). "In colorectal cancer, ZKSCAN3 (ZNF306) expression was elevated and under-expression of ZKSCAN3 reduced tumorigenicity." (PMID 24236047, 2013). "In colorectal cancer and liver cancer, ZKSCAN3 promotes the expression of integrin-β4." (PMID 41393507, 2025). "In addition, ZKSCAN3 (ZFN306) also contributes to tumor metastasis in colorectal cancer cells, prostate cancers, and hepatocellular carcinoma." (PMID 35038288, 2022). "ZKSCAN3 was initially identified as a driver of colorectal cancer; however, it also plays an important role in cancer cell proliferation, migration, and metastasis in several human malignancies, including colon, bone marrow, prostate, bladder, and cervical cancers." (PMID 36012568, 2022). "Moreover, ZKSCAN3 has been reported as a novel driver of colorectal cancer progression and to promote prostate cancer cell migration." (PMID 30241382, 2018). "Interestingly, ZKSCAN3 is known to be involved in the progression of colorectal carcinoma." (PMID 36986600, 2023). "Within the scope of colorectal cancer (CRC), ZKSCAN3 demonstrates heightened expression in invasive cells and modulates the expression of genes, including VEGF and ITGβ4, which contribute to tumor growth." (PMID 39519085, 2024). "For instance, in the context of colorectal cancer (CRC), overexpression of ZKSCAN3 has been shown to promote anchorage-independent growth in vitro, as well as tumor growth at the primary site and liver metastasis in vivo through an orthotopic tumor model." (PMID 39519085, 2024). "Therefore, ZKSCAN3 may be used as an early tumor marker for colorectal cancer." (PMID 36012568, 2022). "For instance, ZKSCAN3 (ZNF306) promotes cell growth, migration, angiogenesis and proteolysis in colorectal cancer." (PMID 31160893, 2019).
bladder cancer (8 papers, 2016 to 2025). "ZKSCAN3 has been implicated in the progression of several types of malignancies, including prostate cancer, as well as bladder cancer, colon cancer, multiple myeloma, and breast cancer." (PMID 32824199, 2020). "Meanwhile, copy number gain in the chromosome 6p22 region, where the ZKSCAN3 gene resides, in bladder cancer has been shown to correlate with the risk of disease progression." (PMID 27447553, 2016). "Moreover, ZKSCAN3 knockdown was associated with down-regulated expression of oncogenes and up-regulated expression of tumor suppressor genes in bladder cancer cells." (PMID 27447553, 2016). "In vivo experiments further confirmed that ZKSCAN3-shRNA-treated bladder cancer cells had significantly diminished tumorigenicity in a xenograft mouse model, as evidenced by a reduction in tumor size and malignancy." (PMID 40723888, 2025). "In bladder cancer, the oncogenic function of ZKSCAN3 is similar to its mode of action in prostate cancer." (PMID 40723888, 2025). "The independent pro-carcinogenic mechanism and therapeutic potential of RNA interference established by ZKSCAN3 in bladder cancer provide an important basis for exploring its interaction with other oncogenic signaling pathways." (PMID 40723888, 2025). "The copy number of ZKSCAN3 is increased in a subset of malignancies, including colon cancer, cervical cancer, bladder cancer, and prostatic cancer." (PMID 36012568, 2022). "We first examined the expression of ZKSCAN3 in human bladder cancer cell lines, UMUC3, 647V, and 5637, as well as an immortalized human normal urothelial cell line, SVHUC, by western blotting and reverse transcription (RT)-polymerase chain reaction (PCR)." (PMID 27447553, 2016). "To see if ZKSCAN3 is involved in bladder cancer cell migration and invasion, we performed a scratch wound healing assay and a transwell invasion assay, respectively, in UMUC3 and 647V expressing either ZKSCAN3-shRNA or control-shRNA." (PMID 27447553, 2016). "Further assessment of the functions of ZKSCAN3 is required to determine its biological significance in bladder cancer." (PMID 27447553, 2016). "We further demonstrated, using bladder cancer lines, that ZKSCAN3 knockdown resulted in significant reduction of cell viability, colony formation, cell migration, cell invasion, and the expression of MMP-2/MMP-9, as well as significant induction of apoptosis." (PMID 27447553, 2016). "We found that ZKSCAN3 silencing correlated with the down-regulation of NF-κB expression in bladder cancer cells." (PMID 27447553, 2016). "In the current study, we aimed to determine the functional role of ZKSCAN3 in bladder cancer progression." (PMID 27447553, 2016). "For validating ZKSCAN3 expression in different grades and stages of bladder tumors, we stained another bladder cancer TMA." (PMID 27447553, 2016). "Frequent amplification of chromosome 6p22 on which the ZKSCAN3 gene is located has been detected in various malignancies, including bladder cancer." (PMID 27447553, 2016). "In mouse xenograft models for bladder cancer, ZKSCAN3 knockdown was also found to considerably retard tumor formation and subsequent tumor growth." (PMID 27447553, 2016). "Overall, ZKSCAN3 expression was significantly elevated in bladder cancer, compared with adjacent benign tissue (P=0.008)." (PMID 27447553, 2016). "These in vivo data further suggest that ZKSCAN3 silencing inhibits the development and progression of bladder cancer." (PMID 27447553, 2016). "Previous studies showed that silencing ZKSCAN3 by small hairpin RNAs (shRNAs) in bladder cancer cells (UC13) can promote senescence of them, which may be due to the degradation of lamin B1 via autophagy, a type of selective autophagy—nuclear autophagy." (PMID 37175493, 2023). "In summary, ZKSCAN3 appears to be activated in bladder cancer and promotes tumor growth." (PMID 27447553, 2016).
bladder cancer (continued). "Based on the previous and current findings, ZKSCAN3 may represent not only a useful biomarker of bladder cancer but also a promising therapeutic target." (PMID 27447553, 2016). "Our findings may therefore offer a potential therapeutic strategy for bladder cancer via targeting ZKSCAN3 signaling." (PMID 27447553, 2016). "Correspondingly, ZKSCAN3 overexpression could strongly induce the proliferation and migration of bladder cancer cells." (PMID 27447553, 2016). "In the current study, we investigated whether ZKSCAN3 was expressed in human bladder cancer and could affect its outgrowth." (PMID 27447553, 2016). "The “autophagy-activated-oncogenic” paradox of ZKSCAN3 in pancreatic cancer challenged the classical perception of its unidirectional pro-carcinogenic function in solid tumors, whereas the mode of action of ZKSCAN3 in bladder cancer returned to the conserved characteristics of oncogenic factors." (PMID 40723888, 2025). "However, the status of ZKSCAN3 expression in bladder cancer and its biological function in tumor progression remain largely unknown." (PMID 27447553, 2016). "We further examined whether ZKSCAN3 overexpression could induce the growth of bladder cancer cells." (PMID 27447553, 2016). "Thus, ZKSCAN3 inhibition has the potential of being a therapeutic approach for bladder cancer." (PMID 27447553, 2016). "By silencing ZKSCAN3, the colony formation ability, cell viability, and invasive migration properties of UMUC3 and 647V bladder cancer cells were significantly inhibited, which in turn blocked the tumor growth and metastatic process." (PMID 40723888, 2025). "Suppressing ZKSCAN3 in UMUC3 and 647V bladder carcinoma cells induces apoptosis by significantly reducing colony formation, cell viability, invasion, and migration." (PMID 39519085, 2024). "Two bladder cancer cell lines, UMUC3 and 647V, were found to strongly express ZKSCAN3 protein/mRNA, whereas its expression in 5637 bladder cancer and SVHUC normal urothelium cell lines was very weak." (PMID 27447553, 2016). "The expression status of ZKSCAN3, a zinc-finger transcription factor containing KRAB and SCAN domains, as well as its biological significance, in human bladder cancer remains largely unknown." (PMID 27447553, 2016). "In the present study, we have demonstrated that ZKSCAN3 expression is elevated in bladder cancer, compared with non-neoplastic urothelium, and that ZKSCAN3 silencing results in inhibition of bladder cancer cell proliferation, migration, and invasion." (PMID 27447553, 2016). "Accordingly, functional dysregulation of ZKSCAN3, rather than the simple expression status, may be more closely related to bladder cancer progression." (PMID 27447553, 2016).
multiple myeloma (7 papers, 2016 to 2025). "ZKSCAN3 expression is elevated in various organ cancers, including colon, prostate, bladder, breast, cervix, stomach, myeloma, and liver cancers, and is frequently associated with unfavorable prognostic outcomes." (PMID 39519085, 2024). "Indeed, ZKSCAN3 has been implicated in promoting the progression of a few types of malignancies, including colon cancer, multiple myeloma, and prostate cancer." (PMID 27447553, 2016). "Somatic mutation of ZKSCAN3 gene was also found in multiple myeloma." (PMID 27447553, 2016). "Together, this evidence reveals a central mechanism by which ZKSCAN3 drives multiple myeloma progression through transcriptional regulation of the CCND2-VEGF signaling axis." (PMID 40723888, 2025). "ZKSCAN3-shRNA also suppressed the proliferation of myeloma cells and increased/decreased G1/S-G2 phase populations, respectively." (PMID 27447553, 2016). "In multiple myeloma, ZKSCAN3 demonstrates important functional characteristics." (PMID 40723888, 2025). "In multiple myeloma, ZKSCAN3 promotes expression of cyclin-D2." (PMID 41393507, 2025). "Moreover, ZKSCAN3 engages with the promoter region of cyclin D2 (CCND2) in multiple myeloma, leading to its upregulated expression compared to normal samples." (PMID 39519085, 2024). "ZKSCAN3 selectively binds to CCND2 promoter sequences in myeloma cells." (PMID 39519085, 2024). "ZKSCAN3 interacts with the CCND2 and VEGF promoters, activating their expression in multiple myeloma." (PMID 39519085, 2024). "ZKSCAN3 was also shown to interact with the cyclin D2 (CCND2) promoter and activate its expression in multiple myeloma, in which ZKSCAN3 is also highly expressed compared to normal samples." (PMID 33672287, 2021). "Overexpression of ZKSCAN3 enhances CCND2 promoter activity and induces protein expression, whereas gene silencing significantly reduces CCND2 levels, which in turn inhibits myeloma cell proliferation." (PMID 40723888, 2025). "While previous studies have explored the role of ZKSCAN3 in various cancers, no study has investigated the sequential genetic alterations in myeloma genomes during the transition from diagnosis to plasma cell leukemia." (PMID 39519085, 2024). "Second, positive signals of ZKSCAN3 transcript and protein were detected in six of eight, including four with increased gene copy number, and eight of ten multiple myelomas, respectively, whereas normal plasma cells were negative for ZKSCAN3." (PMID 27447553, 2016). "The synergistic oncogenic network formed by ZKSCAN3 with EGFR in ovarian cancer reveals a unique mechanism for remodeling the microenvironment through receptor tyrosine kinase signaling in solid tumors, and its functional studies in multiple myeloma further broaden its scope of action." (PMID 40723888, 2025). "Expression levels of ZKSCAN3 are significantly higher in myeloma samples compared to normals." (PMID 39519085, 2024).